MIR6887 (microRNA 6887)
Synonyms: hsa-mir-6887
Gene: MicroRNA gene on chromosome 19 (35,122,700 to 35,122,764, forward strand). Ensembl gene ENSG00000284065.
Homologues: Orthologues: chimpanzee MIR6887 (100% identical).